KLRA1P (killer cell lectin like receptor A1, pseudogene)
Synonyms: Ly49; LY49L; formerly KLRA1; KLRAP1
Gene: Transcribed unprocessed pseudogene on chromosome 12 (10,589,386 to 10,598,209, reverse strand). Ensembl gene ENSG00000256667.
Diseases named in the same sentence as KLRA1P in open-access papers:
KLRA1P is named in the same sentence as 23 diseases in open-access papers, as found by Europe PMC text mining. Sharing a sentence is not in itself a finding about the gene and the disease.
KLRA1P shares sentences with these, for which no sentence is quoted: tumor (20 papers); infection (8); viral infection (7); autoimmune disease (5); lupus (5); Autoimmunity (4); influenza (3); cancer (2); melanoma (2); T cell lymphoma (2); Cancer Metastasis (1); celiac disease (1); cerebral malaria (1); diabetes (1); infectious disease (1); Listeria monocytogenes Infection (1); malaria (1); mammary tumors (1); multiple sclerosis (1); prostate tumor (1); rheumatoid arthritis (1); sarcoma (1); Sepsis (1).